SDC4 (syndecan 4)
Diseases named in the same sentence as SDC4 in open-access papers (continued):
Sharing a sentence is not in itself a finding about the gene and the disease.
liver cancer (4 papers, 2021 to 2024). An epithelial or non-epithelial malignant neoplasm that arises from the liver. "We showed that mutated ß-catenin represses expression of SDC4 and RAB27A, two main actors in exosome biogenesis, in both liver cancer cell lines and HCC patient samples." (PMID 39008536, 2024). "Activated ß-catenin represses SDC4 and RAB27A expression in liver cancer cells." (PMID 39008536, 2024).
liver fibrosis (4 papers, 2017 to 2024). "Further elucidation of the function of Sdc4 in aHSC will make it a new marker for aHSC identification or a potential therapeutic target for liver fibrosis." (PMID 37724132, 2023). "In the present paper, the protein SDC-4 with the highest fold change was selected as the possible target of dioscin against liver fibrosis through inhibiting HSCs migration based on GO classifications." (PMID 29033837, 2017). "All the results indicated that SDC-4 plays important role in dioscin against liver fibrosis through regulating cell adhesion and cell migration." (PMID 29033837, 2017). "Sdc4 and Fetub, blood markers of NAFL in humans and those related to NASH and liver fibrosis were highly expressed in the db-HF group, despite their better fatty liver phenotype." (PMID 38613031, 2024). "The validation cohort showed GPC3 was negatively correlated with all liver fibrosis markers ACTA2, COL1A1, COL1A2, COL3A1 and ductular reaction markers KRT7 and KRT19, while SDC4 was positively correlated with ductular reaction index KRT19." (PMID 36816373, 2023).
Pancreatic Cancer (4 papers, 2021 to 2026). "A direct link between the presence of syndecan-4 in PSCs and pancreatic cancer progression has not been described yet." (PMID 33669066, 2021).
psoriasis (4 papers, 2013 to 2025). An autoimmune condition characterized by red, well-delineated plaques with silvery scales that are usually on the extensor surfaces and scalp. "Concerning miRNAs, it has been identified that hsa-miR-19a-3p has great potential to become a biomarker for psoriasis because it binds to the mRNA of seven genes (CAST, TSC1, SPATA2, ERAP1, TNIP1, ERBB3 and SDC4) thatare associated with psoriasis." (PMID 40725409, 2025). "In this study, we looked for evidence implicating the syndecan-1 and syndecan-4 expressed within the human epidermis with the pathogenesis of psoriasis." (PMID 35742957, 2022). "Our study provides evidence for the involvement of syndecan-1 and/or syndecan-4 in the pathogenesis of psoriasis and could serve as potential targets for treatment." (PMID 35742957, 2022).
rheumatoid arthritis (4 papers, 2018 to 2025). A chronic, systemic autoimmune disorder characterized by inflammation in the synovial membranes and articular surfaces. "Knocking down SDC4 has been shown to diminish the inflammatory response in allergic asthma and rheumatoid arthritis." (PMID 40747330, 2025). "In a mouse model of rheumatoid arthritis syndecan-4 has been identified as a prominent molecule in fibroblast attachment and cartilage damage, a step which is recognised as irreversible and is a ‘point of no return’ in joint destruction in arthritis." (PMID 29498714, 2018). "On the contrary, some other studies reported that SDC4 could promote allergic airway inflammation or initiate the inflammatory response of rheumatoid arthritis." (PMID 35842658, 2022). "Together these exciting findings indicate that targeting the RPTPσ syndecan-4 interaction in FLS could be an effective treatment for rheumatoid arthritis." (PMID 29498714, 2018).
Arthritis (3 papers, 2014 to 2022). Inflammation of a joint. "Syndecan-4 null animals are resistant to collagen-induced arthritis which is T and B cell dependent and this correlated with reduced chemotactic migration in syndecan-4 deficient B cells." (PMID 33561383, 2021). "Syndecan-4 null animals are protected in models of arthritis and disruption of an interaction between syndecan-4 and the protein tyrosine phosphatase receptor PTPRσ on fibroblast-like synoviocytes is associated with more severe disease progression in mouse models." (PMID 33561383, 2021). "This suggests that sdcs may be involved in various aspects of joint inflammation and damage in arthritis, with endothelial sdc-3 functioning in leukocyte recruitment and fibroblast sdc-4 in cartilage destruction." (PMID 25015005, 2014).
bacterial pneumonia (3 papers, 2017 to 2021). Acute infection of the lung parenchyma caused by bacteria (e.g., Streptococcus pneumoniae, Haemophilus influenzae, Chlamydia pneumoniae, Mycoplasma pneumoniae, and Legionella pneumophila). "Adult patients (average age: 67.1 ± 3.1 years) with bacterial pneumonia were found to have elevated serum syndecan-4 levels (an HSPG)." (PMID 34573906, 2021). "Second, we also need to consider the possible participation of bacterial pneumonia, as our previous study showed increased serum syndecan-4 levels under this condition." (PMID 28467516, 2017). "For example, the DSPG endocan is elevated in patients with stable chronic obstructive pulmonary disease (COPD) (n = 47), and syndecan-4, an HSPG, is elevated in response to bacterial pneumonia (n = 30)." (PMID 34573906, 2021). "Additionally, serum syndecan-4 levels had a negative correlation with severity, and syndecan-4 knockout mice had higher mortality rates than control mice when infected, suggesting that syndecan-4 plays a protective role in bacterial pneumonia." (PMID 34573906, 2021).
bladder cancer (3 papers, 2021 to 2025). "The expression of syndecan-1, -2 and -3 is decreased while syndecan-4 is increased in bladder cancers compared to normal tissues." (PMID 33810567, 2021). "αVβ1 integrin and syndecan-4 are key players of the interaction with vitronectin in bladder cancer cells." (PMID 33810567, 2021). "Functionally, interactions of syndecan-4 and angiomodulin have been found to be responsible for the formation of cord-like structures in the human bladder carcinoma cell line ECV-304." (PMID 33810567, 2021).
breast adenocarcinoma (3 papers, 2017 to 2021). "Overexpression of SDC4 decreases the invasion of breast adenocarcinoma cells into 3D collagen matrix, whilst SDC4 silencing increases the invasiveness." (PMID 34282767, 2021). "Syndecan-4 promotes cytokinesis in a phosphorylation-dependent manner in MCF-7 breast adenocarcinoma cells, which shed the ectodomain of syndecan-4 periodically in a cell cycle-dependent way, reaching the maximum at the G2/M phase." (PMID 33810567, 2021). "Our results unravelled a novel regulatory mechanism of the basal Rac1 activity that was mediated by SDC4 in a phosphorylation- and PDZ interaction-dependent manner in MCF-7 breast adenocarcinoma cells." (PMID 29121646, 2017).
breast tumors (3 papers, 2013 to 2025). "Whether serum SDC4 levels reflect syndecan shedding from HR + breast tumors or serve as markers of systemic inflammation influencing cancer risk remains unclear and, to our knowledge, unexplored." (PMID 40694191, 2025). "The prometastatic effect exerted by SDC4 was mediated via its interaction with Autotaxin-β, a member of the nucleotide pyrophosphatases phosphodiesterase family involved in the formation of spontaneous breast tumors and metastasis, suggesting a functional crosstalk between SDC4 and Autotaxin-β." (PMID 36980680, 2023). "In ER+ breast tumors E2 exerts a protective role since it regulates the expression both of MMP-2 and MMP-9 as well as syndecan-4 and, therefore, limits the ability of cells to invade the adjacent tissues." (PMID 23936773, 2013).
cervical carcinoma (3 papers, 2021 to 2025). A carcinoma arising from either the exocervical squamous epithelium or the endocervical glandular epithelium. "The upregulated ligand receptor pairs in the cervical cancer group were SPP1 − CD44, FN1 − SDC4, FN1 − SDC1, FN1 − CD44, CD99 − CD99, and the downregulated ligand receptor pairs were PPIA – BSG, LGALS9 − P4HB, LGALS9 − CD44." (PMID 41384115, 2025).
chronic heart failure (3 papers, 2016 to 2023). "Sdc4-Tg-NFAT-luc mice showed increased LV and LW weights upon pressure overload compared to NFAT-luc controls (Table SII), suggesting exacerbated congestive heart failure after AB in mice with Sdc4 overexpression." (PMID 36205855, 2022).
diabetic retinopathy (3 papers, 2021 to 2025). "On the other hand, SDC4, the transmembrane proteoglycan overexpressed in diabetic retinopathy, exhibits astrocyte-specific expression in the brain and limited expression in neurons." (PMID 36834552, 2023). "Enhanced transduction of AAV2 and 9 in diabetic retinopathy is attributed to several overexpressed receptors, such as syndecan-4 (SDC4), glypican-1, and perlecan for AAV2 and 37- and 67-kDa laminin for AAV9." (PMID 36834552, 2023).
disc degeneration (3 papers, 2013 to 2022). "In our experiment, using a syndecan-4 siRNA for early intervention in disc degeneration resulted in an increase in NPC numbers and cartilage-like matrix production compared to those in the control group." (PMID 32071547, 2020). "Our study found substantial upregulation of Sdc4, confirming the important role Adamts play in ECM regulation during disc degeneration." (PMID 24171898, 2013).
fibrosis (3 papers, 2019 to 2023). the formation of excess fibrous connective tissue in an organ or tissue in a reparative or reactive process. "This scenario is supported by recent findings that SDC4 expression suppresses the development of fibrosis in fibrotic disease models." (PMID 38057316, 2023). "Meanwhile, SDC4 is important in regulating the formation of extracellular matrix, which provides the novel targets for cardiac fibrosis and the subsequent pathological remodeling induced by various stimuli." (PMID 36341343, 2022).
non-alcoholic fatty liver disease (3 papers, 2022 to 2025). "Circulating Sdc4 levels are positively associated with diabetic kidney disease and non-alcoholic fatty liver disease (NAFLD)." (PMID 40180176, 2025). "Moreover, the extracellular domain of SDC4 can be released into the serum and has been used as a potential biomarker for the diagnosis of non-alcoholic fatty liver disease." (PMID 36816373, 2023).
pancreatic adenocarcinoma (3 papers, 2020 to 2025). "High expression of SDC-4 was found to be related to clinicopathological features and poor prognosis of pancreatic adenocarcinoma." (PMID 40416874, 2025). "Other tumor types with a significant correlation with the hypoxia signature were thymoma (THYM) and THCA for SDC3, and TGCT and pancreatic adenocarcinoma (PAAD) for SDC4." (PMID 33117401, 2020).
periodontitis (3 papers, 2019 to 2024). An acute or chronic inflammatory process that affects the tissues that surround and support the teeth. "However, inhibiting autophagy with 3-MA abolished osteoclast differentiation which was enhanced by SDC4, indicating that autophagy might promote the osteoclast differentiation during periodontitis." (PMID 35846745, 2022). "The research found that Syndecan 4 (SDC4), a member of the syndecan family, was highly expressed in the experimental periodontitis rat model." (PMID 35846745, 2022).
ureteric obstruction (3 papers, 2016 to 2022). "We have recently reported that knock-out (KO) of the HSPG receptor syndecan-4 (Sdc4) ameliorates fibrosis in the murine unilateral ureteric obstruction (UUO) and aristolochic acid nephrotoxicity (AAN) models, and that this is connected with a lower level of extracellular TG2 protein and activity." (PMID 27694984, 2016).
aristolochic acid nephropathy (2 papers, 2017 to 2019). "Syndecan-4 knockout was protective in two experimental models of CKD, the unilateral ureteric obstruction (UUO) and aristolochic acid nephropathy (AAN) models." (PMID 30621228, 2019).
atopic dermatitis (2 papers, 2017 to 2022). "For example SDC-4 (syndecan-4) mRNA levels were increased in atopic dermatitis compared with normal skin samples and the inflammatory mediators IL-17, IL-20, IL-24, IL-31, and IL-33 were also elevated in atopic dermatitis." (PMID 29383128, 2017). "Interestingly, an increase of syndecan-4, was previously observed in the serum and lesional skin of patients with atopic dermatitis suggesting that the presence of this molecule might differentiate between the two skin diseases." (PMID 35742957, 2022).
autoimmune disease (2 papers, 2023 to 2024). A disorder resulting from loss of function or tissue destruction of an organ or multiple organs, arising from humoral or cellular immune responses of the individual to their own tissue constituents. "Furthermore, the interaction between GPNMB on antigen-presenting cells and syndecan-4 on T cells inhibits T-cell activation, which is relevant in T cell-driven autoimmune diseases." (PMID 39263169, 2024).
cardiomyopathies (2 papers, 2023 to 2024). "To better understand the underlying mechanism of MLP-associated cardiomyopathy and the potential involvement of syndecan-4, we employed adult cardiomyocytes to determine the subcellular fraction in which this interaction occurs." (PMID 38891079, 2024). "To better understand the underlying molecular mechanism of MLP-associated cardiomyopathy and the potential involvement of syndecan-4, we tested whether the H9c2 rat ventricular cardiomyoblast cell line could be used as a model." (PMID 38891079, 2024). "To gain deeper insight into the role of the syndecan-4–MLP interaction and its potential involvement in MLP-associated cardiomyopathy, we have here investigated the syndecan-4–MLP interaction in primary adult rat cardiomyocytes and the H9c2 cell line." (PMID 38891079, 2024). "To further characterize the syndecan-4–MLP interaction sites, MLP oligomerization, and the effect of human cardiomyopathy-associated MLP mutations, we have presently explored MLP, syndecan-4, and their interaction in adult primary rat cardiomyocytes and the H9c2 rat cardiomyoblast cell line." (PMID 38891079, 2024). "MLP mutations were also linked to changes in MLP oligomerization and self-association, which may be essential for its interaction with syndecan-4 and a critical molecular mechanism of MLP-associated cardiomyopathy." (PMID 38891079, 2024). "Thus, we were unable to conclude whether serum syndecan-4 was increased vs. the controls in our cardiomyopathy or acute MI patient cohorts." (PMID 37189684, 2023).
diabetic kidney disease (2 papers, 2020 to 2025). Progressive kidney disorder caused by vascular damage to the glomerular capillaries, in patients with diabetes mellitus. "Shed glycocalyx components, including syndecan-4, warrant further investigation as potential biomarkers for diabetic kidney disease and associated cardiovascular complications." (PMID 32037077, 2020). "Matrix metallopeptidase 9 (Mmp9)-mediated Sdc4 shedding leads to glomerular endothelial glycocalyx damage and increased albumin permeability, exacerbating the development of diabetic kidney disease (DKD)." (PMID 40180176, 2025).
endometriosis (2 papers, 2019 to 2021). The growth of functional endometrial tissue in anatomic sites outside the uterine body. "Our previous work demonstrated that syndecan-4 depletion decreased the expression of MMP3 in endometriosis, resulting in decreased invasive growth, and suggesting possible feedback loops." (PMID 33810567, 2021). "In endometriosis, a disease characterized by invasive growth of endometrial tissue at ectopic sites, syndecan-4 is upregulated along with constituents of TGF-beta signaling, and modulates invasion via regulation of MMP and RAC1 expression." (PMID 33810567, 2021).
gastric cancer (2 papers, 2016 to 2025). A primary or metastatic malignant neoplasm involving the stomach. "The proteoglycans syndecan-1, syndecan-2, syndecan-4, glypican-1 and glypican-3 were upregulated in gastric cancer with high in vitro and in vivo peritoneal seeding potential, suggesting a role for these molecules in peritoneal dissemination." (PMID 27074785, 2016).
Glucose intolerance (2 papers, 2022 to 2025). Glucose intolerance (GI) can be defined as dysglycemia that comprises both prediabetes and diabetes. "Recently, we demonstrated abnormal glucose intolerance owing to impaired insulin secretion in a glucose tolerance test with 8-week-old male SDC4-KO mice of the C57BL/6J (B6) strain." (PMID 36292936, 2022). "In addition, no glucose intolerance was observed in 8-week-old male SDC4-KO mice of the Institute of Cancer Research (ICR) strain, which differs from the B6 strain." (PMID 36292936, 2022).
Hepatic steatosis (2 papers, 2019 to 2025). Steatosis is a term used to denote lipid accumulation within hepatocytes. "In mouse models, a novel hepatokine called SDC4 responds to exercise and reduces fatty acid uptake and liver steatosis, offering potential insights into novel targets for NAFLD treatment by elucidating the proteome alterations in hepatocytes due to exercise." (PMID 40329313, 2025).
intervertebral disc degeneration (2 papers, 2020 to 2022). "SDC4 has an important effect on intervertebral disc degeneration induced by inflammatory factors, such as TNF-α and IL-1β." (PMID 36506585, 2022). "Several studies have demonstrated the positive relationship between syndecan-4 expression and intervertebral disc degeneration." (PMID 32071547, 2020). "SDC4 could form positive feedback with inflammatory factors and mediate intervertebral disc degeneration through inflammatory pathways together." (PMID 36506585, 2022). "Moreover, CCL5, AQP3 and SDC4 may improve the chemotaxis of stem cell migration for self-healing of damaged disc tissue, increase water uptake by nucleus accumbens cells, and inhibit the inflammatory response, thus delaying the process of intervertebral disc degeneration." (PMID 36506585, 2022). "Thus, SDC4 can accelerate EMC degradation and promote intervertebral disc degeneration by interacting with pro-inflammatory factors and matrix metalloproteinases." (PMID 36506585, 2022).
multiple myeloma (2 papers, 2020). "FACS analyses revealed that U266 cells express the highest levels of syndecan-1, as would be expected for myeloma cells, whereas U87 cells express high levels of syndecan-4." (PMID 33585253, 2020). "For instance, the interaction of SDC4 and RSPO3 was shown to regulate WNT/planar cell polarity (PCP) signaling during Xenopus gastrulation by a process that requires clathrin-mediated endocytosis, and SDC1 was shown to promote signaling in multiple myeloma by presenting WNTs and RSPOs." (PMID 32432544, 2020).
Myocardial fibrosis (2 papers, 2017 to 2020). "Thus, the aim of this study was to evaluate the potential role of serum syndecan-4 as a novel biomarker for disease severity in CD, by concentrations with myocardial fibrosis and left ventricular ejection fraction (LVEF)." (PMID 29232393, 2017). "Our results demonstrate the lack of correlations between serum syndecan-4, myocardial fibrosis and cardiac dysfunction in subjects with Chagas disease." (PMID 29232393, 2017). "Syndecan-4 serum concentrations did not correlate with presence or absence of myocardial fibrosis (P = 0.386) nor disease severity in subjects with Chagas disease (P = 0.918)." (PMID 29232393, 2017). "In conclusion, our study showed a lack of correlation between either the degree of myocardial fibrosis or the LVEF and the serum concentration of syndecan-4 in subjects with Chagas disease." (PMID 29232393, 2017).